MPO (myeloperoxidase)
Diseases named in the same sentence as MPO in open-access papers (continued):
Sharing a sentence is not in itself a finding about the gene and the disease.
glioma (13 papers, 2020 to 2024). A benign or malignant brain and spinal cord tumor that arises from glial cells (astrocytes, oligodendrocytes, ependymal cells). "Furthermore, CD66b, MPO, and H3cit expression levels were positively associated with glioma grade and poor prognosis in patients." (PMID 38167409, 2024). "Compared with NHAs, COL22A1, and IGF2BP2 mRNA levels were significantly increased in the glioma cell lines, while MPO levels were instead similar." (PMID 37737709, 2023). "Enhanced brain infiltration of CD66b+ granulocytes with intense staining for CitH3 and MPO has been described in the brain tissue of high-grade gliomas compared to low-grade ones." (PMID 35844591, 2022). "Neutrophils isolated from each glioma stage were stained with MPO and citH3 and analyzed by confocal microscopy." (PMID 34288521, 2021). "Our findings provided mechanistic insight into the role that MPO and oxidative stress play in glioma growth and support future investigations of D-mannose as a potential low-cost treatment option for this devastating disease." (PMID 34944979, 2021). "On the other hand, when MPO activity is acutely increased in established tumors, as was the case in our study with implanted glioma treated with D-mannose, the increased acute inflammatory response becomes tumoricidal." (PMID 34944979, 2021). "We demonstrated that D-mannose unexpectedly increased MPO activity in glioma, which markedly slowed glioma growth in a mouse model." (PMID 34944979, 2021). "Taken together, these results revealed that D-mannose treatment decreased the number of pro-inflammatory cells recruited to the glioma microenvironment, but each of these cells secreted more active MPO." (PMID 34944979, 2021). "We found that D-mannose slowed glioma growth by increasing MPO activity and oxidative stress in the glioma microenvironment." (PMID 34944979, 2021). "Despite the increase in total MPO activity, there were fewer MPO+ cells found in the glioma microenvironment, suggesting that each MPO+ cell secretes more active MPO." (PMID 34944979, 2021). "Then control neutrophils isolated from each glioma stage were incubated with Phorbol‐12‐myristate‐13‐acetate (25 nM) and stained with MPO and citH3 and analyzed by confocal microscopy." (PMID 34288521, 2021). "As MPO is normally a highly oxidizing, deleterious enzyme, such an upregulation of MPO activity is potentially also harmful to the host in addition to the glioma." (PMID 34944979, 2021). "We identified direct and indirect mechanisms by which D-mannose can modulate MPO activity in the glioma microenvironment." (PMID 34944979, 2021). "We stained glioma sections for the neutrophil marker myeloperoxidase (MPO) and found that MPO-positive cells localized to TAMRA-FP hotspots." (PMID 32190011, 2020). "Regarding the role of neutrophil activation markers, we observed an increase in MPO and calprotectin levels in glioma patients who underwent post-surgical PE." (PMID 32545233, 2020). "At the screening stage (10 glioma patients) we attained a reliable multivariable elastic net logistic regression model of post-surgical PE with cfDNA and MPO as predictors (AUC = 0.88, 95% CI [0.63, 1.00], p = 0.028)." (PMID 32545233, 2020). "However, recent investigations have unveiled the presence of NETs within grade IV glioma tissues, discerned through immunostaining techniques targeting myeloperoxidase (MPO) and citrullinated histone H3 (CitH3)." (PMID 38732975, 2024). "Additionally, IGF2BP3 showed a positive correlation with CD66b, MPO, and H3cit expression in glioma patients, indicating its potential role in NETosis induction." (PMID 38167409, 2024). "Interestingly, animal experiments showed that MPO exhibited antitumor activity against glioma after radiotherapy." (PMID 37737709, 2023). "Likewise, further research is needed to assess the potential pro-angiogenic actions of MPO in advanced glioma." (PMID 37737709, 2023).
glioma (continued). "This increased host immune response acted to reduce tumor size, suggesting that increasing MPO activity such as through D-mannose administration may be a potential new therapeutic direction for glioma treatment." (PMID 34944979, 2021). "However, this increase appeared to be tempered by limiting this response to the glioma microenvironment and that there were fewer number of MPO+ cells, likely due to the effect D-mannose has on MPO signaling." (PMID 34944979, 2021). "Instead, we found that D-mannose increased MPO activity in the glioma microenvironment." (PMID 34944979, 2021). "In this study, we found that increasing MPO activity decreased glioma size." (PMID 34944979, 2021). "As such, we expected D-mannose treatment to decrease MPO activity in the glioma microenvironment." (PMID 34944979, 2021). "Furthermore, we attained a predictive model for post-surgical PE in glioma that includes cfDNA and MPO as predictors." (PMID 32545233, 2020). "Although the origin of these neutrophil activation markers could be other than neutrophils, we observed a significant correlation between cfDNA and MPO levels, suggesting that neutrophils may be the source of these makers in plasma of glioma patients." (PMID 32545233, 2020). "We found a significant correlation between cfDNA and MPO levels (Spearman r = 0.323, p = 0.022), suggesting that neutrophils may be the source of these makers in plasma of glioma patients." (PMID 32545233, 2020). "Thus, MPO and MPO-mediated products likely play a role in the glioma immune microenvironment." (PMID 34944979, 2021). "Furthermore, a good prediction could also be obtained in glioma patients with markers of neutrophil activation, cfDNA and MPO, measured before surgery." (PMID 32545233, 2020). "As expected, we found that D-mannose treatment decreased the number of MPO+ cells and slowed glioma progression compared to PBS-treated control animals with gliomas." (PMID 34944979, 2021). "Immunofluorescence analysis revealed higher levels of NETs in grade IV glioma tissues than in grade II or grade III glioma tissues, as determined by staining for MPO and citrullinated histone H3 (citH3)." (PMID 32296583, 2020). "Using a glioma stem cell model in immunocompetent mice, we induced gliomas in the brain and tracked MPO activity in vivo with and without D-mannose treatment." (PMID 34944979, 2021). "Thus, infiltration of the MPO+ neutrophils was evident in the gliomas in SorLA-KO brains, while it did not occur in the WTs and in the contralateral hemispheres." (PMID 38499808, 2024).
Hepatic steatosis (13 papers, 2012 to 2025). Steatosis is a term used to denote lipid accumulation within hepatocytes. "Next, the effects of MPO deficiency on the development of hepatic steatosis were examined in more detail." (PMID 23285030, 2012). "In contrast, the addition of Hon to the Fru-enriched drinking water diminished the development of fatty liver and inflammatory processes, such as the increase in the number of neutrophils and MPO activity, as well as of PAI-1 and IL-6 protein concentration in liver tissue." (PMID 39987978, 2025). "Also, co-administration of chronic ethanol and methamphetamine significantly increased the levels of MDA, myeloperoxidase (MPO), IL1β and TNFα and promoted hepatic steatosis, necrosis and fibrosis by modulating AKT/PI3K and mitogen-activated protein kinase (MAPK) signaling in rats." (PMID 41154722, 2025). "IF staining of the neutrophil markers CD11b and MPO revealed a significant increase in neutrophil infiltration in the CS group, which was partially reversed by HOPE in fatty liver subjected to IRI." (PMID 39617791, 2024). "We did not observe that ABCB10 loss worsened liver neutrophil inflammation or metabolism in ASH, as no upregulation in liver MPO content, no decreases in mitochondrial fat oxidation capacity and no exacerbation of hepatic steatosis were observed in ABCB10 L-KO mice under the NIAAA model." (PMID 38290384, 2024). "Hepatic steatosis was accompanied with an elevation in the hepatic biomarkers of redox status evidenced by a drop in the hepatic catalase and GST levels significantly by about 75% and 57%, respectively, accompanied by an increase in the hepatic MPO level by 3.4 folds." (PMID 32420546, 2020).
neuropathy (13 papers, 2008 to 2025). A disorder affecting the nervous system that manifests with pain, tingling, numbness, and/or muscle weakness. "The CCI-induced neuropathy has also been associated with significant inflammation as assessed by marked increase in MPO and TNF-α levels." (PMID 28103857, 2017). "Electrophysiological studies and serological testing, particularly MPO-ANCA, were pivotal in distinguishing EGPA-associated neuropathy from diabetic neuropathy." (PMID 41480456, 2025). "More specifically, a recent study investigated the clinicopathologic features of EGPA-associated neuropathy with and without MPO-ANCA." (PMID 35833130, 2022). "Moreover, our studies are the first to show that inhibition of MPO activity by 4-aminobenzoic hydrazide reduces mechanical and thermal hypersensitivity, confirming the important role of neutrophils in neuropathy." (PMID 34795678, 2021). "Overlap between endotypes is common (e.g., MPO-ANCA positivity with eosinophilic myocarditis, or ANCA-negative disease with neuropathy)." (PMID 41303621, 2025). "Changes in the level of this chemokine in the spinal cord were observed between the 2nd and 28th days of neuropathy induced by sciatic nerve injury, which coincided with changes in IBA-1, GFAP and MPO levels." (PMID 36611891, 2022). "In the present case, the perceptive deafness with vertigo corresponded to pathological conditions of CSS, such as increased MPO-ANCA and some inflammatory markers and exacerbated neuropathy of the peripheral nerves." (PMID 22989316, 2012). "Myeloperoxidase assay [(MPO), a specific marker of inflammation] and calcium levels were determined to assess biochemical alterations due to neuropathy." (PMID 21593965, 2008). "In our study, a statistically significant difference was not noted in the MPO ratio between DM patients with and without neuropathy (p > 0.05)." (PMID 26719776, 2015).
acute leukemia (12 papers, 2012 to 2025). A clonal (malignant) hematopoietic disorder with an acute onset, affecting the bone marrow and the peripheral blood. "High-level expression of myeloperoxidase in acute leukemia expressing B cell markers favors a diagnosis of B/myeloid mixed-phenotype acute leukemia (MPAL) or acute myeloid leukemia, which are discussed elsewhere in this publication." (PMID 40227608, 2025). "In particular, patient #11944 expressed CD2, CD7 and TdT in 94%, 82% and 26% of cells, respectively, while patient #11945 was also positive for CD3 cytoplasmatic expression, TdT and MPO, with a diagnosis of T/myeloid mixed phenotype acute leukemia (T/M MPAL)." (PMID 31817495, 2019). "Myeloperoxidase is a marker for granulocytes, and its presence can be used to distinguish between myeloid and lymphatic origins of acute leukemias." (PMID 30975897, 2019). "Myeloperoxidase (MPO)/lysozyme (LYZ) and marginal zone B and B1 cell-specific protein (MZB1)/brain and acute leukemia, cytoplasmic (BAALC) were respectively activated in the granulocyte-macrophage progenitor (GMP) and multilymphoid progenitor (MLP) clusters." (PMID 40036065, 2025). "The marrow was hypercellular with a predominance of myeloperoxidase (MPO)-positive promyelocytes, leading to a provisional diagnosis of acute leukemia, most consistent with APL." (PMID 41552099, 2025). "The new classification system proposes the diagnosis of mixed-phenotype acute leukemia (MPAL) and emphasizes the impact of CD19 for B-cell lineage, CD3/cCD3 for T-cell lineage, and cytoplasmatic myeloperoxidase (MPO) for myeloid lineage, respectively." (PMID 34934076, 2021). "Based on our results, we suggest the use of this limited panel of immunohistochemical markers including MPO, CD20, CD3 and TdT for the routine evaluation of all acute leukemias in paraffin embedded tissues." (PMID 27489589, 2016). "Undifferentiated acute leukemia lacks the expression of lineage-specific markers, including cytoplasmic CD3, myeloperoxidase, multiple B cell markers including CD19, or markers of other lineages, such as NK cells, megakaryocytes, basophils, or plasmacytoid dendritic cells." (PMID 40227608, 2025). "Similarly, the diagnosis of acute leukemia was confirmed by identifying over 20% blasts in the bone marrow, which were characterized as myeloid in origin by positive CD13, CD33, and MPO markers on flow cytometry." (PMID 39619312, 2024). "An example would be an acute leukemia that expresses T lineage markers, but not CD3, myeloid lineage markers, but not myeloperoxidase, and/or B lineage marker CD19, but not other B lineage markers." (PMID 40227608, 2025). "Moreover, the minimal expression or complete absence of myeloperoxidase and aberrant CD7 expression, along with the morphology of the blasts, can present a challenging differential diagnosis with mixed phenotype acute leukemia (myeloid/T)." (PMID 29541391, 2018).
Candida infection (12 papers, 2011 to 2024). "Original studies in MPO-deficient human patients revealed candidiasis as the primary disease presentation and revealed that MPO-deficient PMN function was relatively normal, with some slowed kinetics in killing Staphylococcusaureus." (PMID 39133648, 2024). "Further studies showed that MPO- or NADPH oxidase-deficient mice releasing insufficient amounts of NETs eventually died from invasive candidosis, whereas MPO-deficient mice survived infections caused by yeast-locked mutants." (PMID 35784323, 2022). "Decreased myeloperoxidase activity in neutrophils was first reported as a mechanism for susceptibility to Candida infection in 1969." (PMID 32185141, 2020). "Despite its roles in innate immunity, the importance of MPO in preventing infection is unclear, as individuals with MPO deficiency are asymptomatic with the exception of an increased risk of candidiasis." (PMID 31002727, 2019). "To investigate whether MPO plays a protective or pathogenic role during systemic infection, we performed survival experiments in WT and MPO-deficient mice using a model of systemic candidiasis." (PMID 35945238, 2022). "Genetic predisposition to disseminated candidiasis in non-immunocompromised humans has not yet been associated to any particular gene, although individuals presenting impaired phagocyte function are more susceptible to Candida infections, as observed in myeloperoxidase (MPO) deficiency." (PMID 21533108, 2011). "Together, these findings suggested that in systemic candidiasis, neutrophils control splenic colonization and systemic inflammation in an MPO-dependent manner." (PMID 35945238, 2022). "Lack of MPO would thus suggest an impaired microbial killing, in line with that MPO deficiency was originally associated with Candida infection in diabetic patients, even though the majority of affected individuals were clinically healthy." (PMID 37954595, 2023). "Decreased myeloperoxidase (MPO) activity (inability to produce hypochlorous acid) in neutrophils leads to delayed killing of pathogen and makes an individual susceptible to invasive Candida infection." (PMID 34490039, 2021). "Individual_9, who carries the known NM_000250.1:c.1552_1565del variant, is an MPO HKO who did not report episodes of recurrent candidiasis or other severe infections, neither at the first clinical assessment nor at follow-up." (PMID 33727708, 2021). "Non-isolated candida infection can occur due to a phagocyte myeloperoxidase deficiency." (PMID 38515059, 2024). "Similarly, of the myriad of known neutrophil specific immunodeficiencies caused by genetic abnormalities linked to Candida infection, including Dectin-1, CD18, CARD9, MPO, and enzymes of the NADPH oxidase pathway, to date chitotriosidase has not been linked in an increase in fungal susceptibility." (PMID 33796101, 2021). "In systemic candidiasis, microbial capture via the phagocytic receptor SIGNR1 neutralizes myeloperoxidase by facilitating marginal zone infiltration and T cell death-dependent histone release." (PMID 35945238, 2022).
Cognitive impairment (12 papers, 2006 to 2025). Abnormal cognition is characterized by deficits in thinking, reasoning, or remembering. "By focusing on MPO, this study aligns with the emerging paradigm shift in the management of MI-associated cognitive deficits targeting the inflammatory cascade to halt or reverse neurological damage." (PMID 39204198, 2024). "Here we report for the first time that induced MPO deficiency in 5XFAD mouse model of AD, markedly reduced the inflammatory response, and prevented cognitive impairment." (PMID 31611761, 2019). "The substantial decrease in myeloperoxidase levels in the hippocampus and cardiac tissues underscores the anti-inflammatory properties of BETNs, which are crucial for addressing inflammation-related cognitive impairment associated with MI." (PMID 39204198, 2024). "Judging from previous studies and current analysis, we may hypothesize that MPO levels which increase significantly after cardiac surgery may cause blood–brain barrier and neurological damage presenting with cognitive deficits including delirium." (PMID 35175161, 2022). "This study was mainly designed to investigate whether some clinical and individual variables and the occurrence of the -463 G/A promoter polymorphism of the MPO gene may be associated with cognitive impairment in patients with MS." (PMID 16504169, 2006). "Insights gained from molecular docking and dynamic simulations suggest that BET has a strong affinity for MPO, leading to stable complex formation that may translate into a noticeable therapeutic effect, particularly in alleviating MI-associated cognitive impairments." (PMID 39204198, 2024). "Inflammation following MI is a critical driver of cognitive deficits, and MPO, a lysosomal enzyme released by activated leukocytes, has emerged as a significant contributor to oxidative stress and inflammatory responses in the post-MI context." (PMID 39204198, 2024). "Albeit, re-introduction of biologically active MPO to the mice meninges at the time of the haemorrhage elicited cognitive deficit seen in DCI." (PMID 35175161, 2022). "The fact that brains of transgenic APP/PS1 mice contain far higher HOCl concentrations as compared to wt littermates makes it conceivable that MPO derived oxidants have the potential to contribute to induce behavioral and cognitive deficits." (PMID 32050431, 2020). "In addition, circulating MPO was higher among individuals with mild cognitive impairment and Alzheimer’s patients compared to healthy controls." (PMID 36873953, 2023). "We examined the effect of MPO KO on cognitive impairment in 5XFAD mice." (PMID 31611761, 2019). "Our findings suggest that MPO polymorphism is not a risk factor for cognitive impairment in MS." (PMID 16504169, 2006). "Interestingly, in young and aged IP KO ischemic mice, there was a significant increase (p < 0.01) in cognitive deficit, hippocampal CA1 pyramidal neuron death, microglia and MPO activation, while p-CREB was reduced as compared to their corresponding WT controls." (PMID 24634780, 2013).